KAT14 (lysine acetyltransferase 14)
Description:
Component of the ATAC complex, a complex with histone acetyltransferase activity on histones H3 and H4. May function as a scaffold for the ATAC complex to promote ATAC complex stability. Has also weak histone acetyltransferase activity toward histone H4. Required for the normal progression through G1 and G2/M phases of the cell cycle.
Synonyms: ATAC2; CRP2BP; CSRP2BP; dJ717M23.1; PRO1194
Tractability: PROTAC: ubiquitination databases record sites on it.
Gene: Protein-coding gene on chromosome 20 (18,137,228 to 18,188,387, forward strand). Ensembl gene ENSG00000149474.
Subcellular location: Nucleus; Cytoplasm
Pathways (Reactome):
Chromatin organization: HATs acetylate histones
Gene expression (Transcription): Formation of WDR5-containing histone-modifying complexes
Gene Ontology:
Molecular function: histone acetyltransferase activity; protein binding; LIM domain binding; acyltransferase activity, transferring groups other than amino-acyl groups
Biological process: negative regulation of transcription by RNA polymerase II; regulation of cell cycle; regulation of cell division; regulation of DNA-templated transcription; regulation of transcription by RNA polymerase II; regulation of tubulin deacetylation; regulation of embryonic development; chromatin remodeling
Cellular component: ATAC complex; nucleus; mitotic spindle; nucleoplasm; cytoplasm
Genetic constraint (gnomAD): Loss-of-function variants: 66 observed, 81.87 expected, observed/expected ratio (o/e) 0.81, 90% interval 0.66 to 0.99. The upper end of that interval is the gene's LOEUF score, 0.99, which puts it in group 4 of 6, group 1 being the genes least tolerant of losing a copy. Missense variants: 870 observed, 1,022.8 expected, observed/expected ratio (o/e) 0.85, 90% interval 0.8 to 0.9. Synonymous variants: 344 observed, 377.96 expected, observed/expected ratio (o/e) 0.91, 90% interval 0.83 to 1.
Homologues: Orthologues: chimpanzee KAT14 (99% identical), macaque KAT14 (99% identical), dog KAT14 (97% identical), pig KAT14 (96% identical), rat Kat14 (96% identical), mouse Kat14 (95% identical), rabbit KAT14 (92% identical), guinea pig KAT14 (91% identical), tropical clawed frog kat14 (76% identical), zebrafish kat14 (74% identical), Drosophila melanogaster Atac2 (32% identical).
Diseases named in the same sentence as KAT14 in open-access papers:
KAT14 is named in the same sentence as 7 diseases in open-access papers, as found by Europe PMC text mining. Sharing a sentence is not in itself a finding about the gene and the disease. The quoted sentences say what the papers report.
cervical cancer (1 paper, 2023). A primary or metastatic malignant neoplasm involving the cervix. "Among these genes, CSRP2BP (also known as lysine (K) acetyltransferase 14, KAT14) was markedly overexpressed in cervical cancer tissues and cervical cancer cell lines and significantly associated with a poor prognosis and metastasis in cervical cancer patients." (PMID 37845756, 2023).
endometriosis (1 paper, 2024). The growth of functional endometrial tissue in anatomic sites outside the uterine body. "In vivo, Kat14 knockdown ameliorated fibrosis in the ectopic lesions of the endometriosis mouse model." (PMID 38867256, 2024).
KAT14 also shares sentences with these, for which no sentence is quoted: Buruli ulcer (1 paper); cancer (1); liver fibrosis (1); neurological diseases (1); tumor (1).